GGT7 (gamma-glutamyltransferase 7)
Description:
Hydrolyzes and transfers gamma-glutamyl moieties from glutathione and other gamma-glutamyl compounds to acceptors.
Synonyms: GGTL3; GGTL5; D20S101; dJ18C9.2; GGT4
Tractability: Antibody: its Gene Ontology location is reachable by antibodies, with high confidence; UniProt predicts a signal peptide or a membrane-spanning region. PROTAC: ubiquitination databases record sites on it; its protein half-life has been measured.
Target class: Enzyme; Transferase
Gene: Protein-coding gene on chromosome 20 (34,844,714 to 34,872,868, reverse strand). Ensembl gene ENSG00000131067.
Subcellular location: Membrane
Subcellular location (Human Protein Atlas): Vesicles; Nucleoplasm
Pathways (Reactome):
Metabolism: Aflatoxin activation and detoxification; Glutathione synthesis and recycling
Drug ADME: Paracetamol ADME
Gene Ontology:
Molecular function: protein binding; glutathione hydrolase activity
Biological process: negative regulation of response to oxidative stress; leukotriene D4 biosynthetic process; glutathione catabolic process; glutathione metabolic process
Cellular component: membrane
Genetic constraint (gnomAD): Loss-of-function variants: 23 observed, 47.92 expected, observed/expected ratio (o/e) 0.48, 90% interval 0.34 to 0.68. The upper end of that interval is the gene's LOEUF score, 0.68, which puts it in group 2 of 6, group 1 being the genes least tolerant of losing a copy. Missense variants: 637 observed, 738.96 expected, observed/expected ratio (o/e) 0.86, 90% interval 0.81 to 0.92. Synonymous variants: 343 observed, 330.47 expected, observed/expected ratio (o/e) 1.04, 90% interval 0.95 to 1.13.
Homologues: Orthologues: macaque GGT7 (99% identical), dog GGT7 (98% identical), rabbit GGT7 (97% identical), chimpanzee GGT7 (97% identical), mouse Ggt7 (96% identical), pig GGT7 (96% identical), rat Ggt7 (95% identical), guinea pig GGT7 (91% identical), tropical clawed frog ggt7 (62% identical), zebrafish GGT7 (48% identical), Drosophila melanogaster Ggt-1 (23% identical), Drosophila melanogaster CG17636 (21% identical). Paralogues in human: GGT1 (26% identical), GGT5 (24% identical), GGT6 (18% identical), GGTLC1 (10% identical), GGTLC2 (9% identical), GGTLC3 (9% identical).
Diseases named in the same sentence as GGT7 in open-access papers:
GGT7 is named in the same sentence as 28 diseases in open-access papers, as found by Europe PMC text mining. Sharing a sentence is not in itself a finding about the gene and the disease. The quoted sentences say what the papers report.
glioblastoma (6 papers, 2021 to 2025). The most malignant astrocytic tumor (WHO grade IV). "Loss of GGT7 may increase the cellular reactive oxygen species levels, inducing glioblastoma occurrence and growth." (PMID 40666499, 2025). "It has been reported that GGT7 expression is higher in the brain than in other tissues and that it has protective effects against glioblastoma growth." (PMID 38550277, 2024). "GGT7 expression is downregulated in glioblastoma but upregulated in liver cancers." (PMID 40094020, 2025). "Another study related to GGT7 and glioblastoma revealed that GGT7 might play a key role in promoting glioblastoma growth by regulating reactive oxygen species (ROS) levels." (PMID 34513707, 2021). "A study related to GGT7 and glioblastomas suggested that GGT7 may play a key role in promoting gliosis by regulating reactive oxygen species (ROS) levels during the growth of glioblastoma by regulating reactive oxygen species (ROS) levels, which play a key role in the growth of glioblastoma." (PMID 41316810, 2025). "GGT7 overexpression predicts poor survival in patients with HCC and glioblastoma." (PMID 41316810, 2025).
diabetes (3 papers, 2021 to 2025). "Nonetheless, polymorphisms rs13041792 of GSS (n = 3,167,810, p = 0.0005) and rs6119534 of GGT7 (n = 1,335,110, p = 0.0002) showed significant associations with an increased body mass index, as a diabetes-related phenotype, in two distinct cohorts of patients, respectively." (PMID 34575035, 2021). "We found that polymorphic variants at GSS and GGT7 genes, alone and in combination, are correlated to the biochemical parameters of redox homeostasis such as ROS and glutathione content as well as to fasting blood glucose and the risk of diabetes." (PMID 34575035, 2021). "Two other genes involved in the glutathione metabolism pathway, CHAC1 and GGT7, were also found to be associated with four different aging outcomes (CHAC1 was associated with frailty index, diabetes, COPD, and BMI; GGT7 was associated with father’s age at death, endometrial cancer and BMI)." (PMID 39398990, 2025).
glioma (3 papers, 2015 to 2025). A benign or malignant brain and spinal cord tumor that arises from glial cells (astrocytes, oligodendrocytes, ependymal cells). "GGT7 was reported to interact with key proteins associated with the progression of lung cancer and is minimally expressed in gliomas compared to that in normal brain tissues." (PMID 34513707, 2021). "GGT7 is a novel GGT family member that is highly expressed in brain and was previously shown to have decreased expression in gliomas." (PMID 25884624, 2015). "GGT7 also differs from the other GGT isoforms, since it is the only isoform to have ~20-fold higher mRNA expression in the brain compared with other normal tissues and has decreased expression in gliomas compared with the normal brain." (PMID 25884624, 2015).
type 2 diabetes (3 papers, 2021 to 2023). "Haplotype analysis revealed that the rs1801310G–rs6088660C–rs13041792A haplotype of GSS increased the risk of type 2 diabetes, whereas, on the contrary, two haplotypes such as rs6119534T–rs11546155G and rs6119534C–rs11546155A of GGT7 decreased disease risk." (PMID 34575035, 2021). "We carried out an in-depth analysis of the literature on the biological functions of genes whose expression is interrelated with polymorphic variants of the GSS and GGT7 genes associated with the development of type 2 diabetes." (PMID 34575035, 2021). "Genetic variation at GSS (rs13041792) and GGT7 (rs11546155 and rs6119534) attracts great interest as the SNPs were found to be associated with the risk of type 2 diabetes in the present study." (PMID 34575035, 2021). "Although the contribution of each SNP of the GSS and GGT7 genes was low or moderate, the joint effects of the genetic variants on the risk of type 2 diabetes were more pronounced, as has been shown by the analysis of SNP–SNP interactions." (PMID 34575035, 2021). "Therefore, in the present study, we used numerous bioinformatics methods for the functional annotation of SNPs to clarify the phenotypic effects of GSS and GGT7 genes showed significant associations with type 2 diabetes." (PMID 34575035, 2021). "Eighteen low- and high-risk genotype combinations were found to be significantly associated with type 2 diabetes and two genotype combinations such as GGT7 rs6119534-C/T × GSS rs1801310-A/A GGT7 and rs6119534-C/T × GSS rs13041792-G/G showed the strongest protective effects against disease risk." (PMID 34575035, 2021). "Therefore, the protective effects of the GGT7 haplotypes against the risk of type 2 diabetes may be attributed to the GGT7-mediated increase in the de novo biosynthesis of glutathione." (PMID 34575035, 2021). "Our recent study discovered that polymorphisms in genes encoding glutathione metabolizing enzymes, such as glutathione synthase (GSS) and gamma-glutamyltransferase 7 (GGT7), are associated with susceptibility to type 2 diabetes." (PMID 37569434, 2023). "The pancreatic expression of genes correlated with the T2D-associated SNPs of GSS and GGT7 has attracted the most attention since the organ is primarily involved in the development of type 2 diabetes." (PMID 34575035, 2021). "The TWAS analysis has shown that the pancreatic expression of EDEM2, MYH7B, MAP1LC3A, and CPNE1 correlated to a carriage of T2D-associated alleles of GSS and GGT7 is associated with the genetic risk of type 2 diabetes." (PMID 34575035, 2021). "The present study investigated whether type 2 diabetes (T2D) is associated with polymorphisms of genes encoding glutathione-metabolizing enzymes such as glutathione synthetase (GSS) and gamma-glutamyl transferase 7 (GGT7)." (PMID 34575035, 2021). "The link between polymorphic genes involved in redox homeostasis, such as GCLM (rs2301022), GGT7 (rs6119534, rs11546155), GSTM1 (+/del), GSTP1 (rs1695, rs1138272), RAC1 (rs7784465), and CYBB (rs5917471), and type 2 diabetes differs in overweight and normal-weight individuals." (PMID 36902173, 2023).
gastric cancer (2 papers, 2024). A primary or metastatic malignant neoplasm involving the stomach. "In gastric cancer, gamma-glutamyltransferase 7 (GGT7) is a tumor-suppressive regulator by interacting with RAB7 and re-locating RAB7 to cytoplasm, leading to enhanced mitophagy and reduced ROS production." (PMID 39035027, 2024). "Wang X. showed that GGT7 could directly bind to RAB7 to induce autophagy, inhibited ROS and MAPK cascade responses, and played a key tumour-suppressive role in gastric cancer." (PMID 38911386, 2024).
pancreatic cancer (2 papers, 2024 to 2025). "Finally, the effect of knocking down TXNDC12 on pancreatic cancer cell functions was able to be reversed by overexpression of GGT7." (PMID 38911386, 2024). "On the contrary, our results showed that GGT7 is upregulated in MIA PaCa-2 and PANC-1 cells, and overexpression of GGT7 can promote the proliferation and migration of pancreatic cancer cells." (PMID 38911386, 2024).
Cirrhosis (1 paper, 2021). A chronic disorder of the liver in which liver tissue becomes scarred and is partially replaced by regenerative nodules and fibrotic tissue resulting in loss of liver function. "In a nationally representative survey that included 14,407 participants in the USA, the level of SUA was associated with the incidence of cirrhosis and elevated serum ALT and GGT7." (PMID 34635716, 2021).
coronary artery disease (1 paper, 2021). "Polymorphisms of the GGT7 have been associated with coronary artery disease, glomerular filtration rate, age at menarche and plasma levels of protein C." (PMID 34575035, 2021).
oral cancer (1 paper, 2016). "Somatic mutations in arachidonic acid metabolism pathway genes, such as PLA2G3, PTGIS and GGT7, prolong post-treatment disease-free survival of patients with oral cancer." (PMID 27888627, 2016).
pancreatic diseases (1 paper, 2025). "Despite the lack of validated protein‐coding activity, GGT6 and GGT7 are highly expressed in tumors, pancreatic diseases, and other disorders, and these genes increase glutathione metabolism, γ‐glutamyl transfer, and leukotriene synthesis through their as yet uncharacterized enzymatic activities." (PMID 41316810, 2025).
prostate carcinoma (1 paper, 2025). A carcinoma that arises from epithelial cells of the prostate gland. "In supporting these data, the NEPC cell line NCI-H660 expressed the highest level of GGT7 expression among all prostate cancer cell lines." (PMID 40094020, 2025). "In this study, we found that GGT7 was slightly downregulated in primary prostate cancer tissues with lymph node invasion and post-surgery residue tumors." (PMID 40094020, 2025). "In conclusion, GGT1/GGT5 expression was upregulated but GGT6/GGT7 expression was downregulated in primary prostate cancers." (PMID 40094020, 2025).
schizophrenia (1 paper, 2021). A major psychotic disorder characterized by abnormalities in the perception or expression of reality. "We also report the following modules of unknown relevance to schizophrenia: Glucuronidation with FDR= 8.81E−04 (genes UGT1A3 to UGT1A10) and Phase II - Conjugation of compounds with FDR= 5E−03 (SLC35B3, GGT7, MGST3, and UGT1A3 to UGT1A10)." (PMID 33892787, 2021).
small cell carcinoma (1 paper, 2025). A neuroendocrine carcinoma composed of small malignant cells which are often said to resemble "oat cells" under the microscope. "Interestingly, GGT7 expression was significantly higher in CRPC patients with neuroendocrinal features and small-cell carcinomas." (PMID 40094020, 2025).
tumor (8 papers, 2015 to 2025). "By modulating GGT7, we demonstrated that the loss of this enzyme increased cellular proliferation and in vivo tumor growth and decreased survival in mice injected intracranially with U87-MG cells." (PMID 25884624, 2015). "Although the findings were not statistically significant (P = 0.08), our data strongly suggest that decreased expression of GGT7 increases GBM tumor growth in vivo." (PMID 25884624, 2015). "Consistently, intracranial injections of U87-MG cells stably transduced with shRNA to GGT7 resulted in an increase in tumor size and a decrease in mouse survival." (PMID 25884624, 2015). "GGT1, a member of the GGT family, has been shown to inhibit ferroptosis via the GSH/GPX4 axis and thus inhibit tumour progression 6, 29, and its amino acid sequence shares 34% homology with its fellow family member GGT7, the protein space structure also has similarity." (PMID 38911386, 2024). "In addition, intracranial injections of U87-MG cells with reduced GGT7 expression increased tumor growth in mice approximately 2-fold, and decreased mouse survival." (PMID 25884624, 2015). "Finally, expression of GGT7 was positively correlated with tumor purity (r = 0.317, P = 1.53e-9), CD8+ T cells (r = 0.254, P = 2.02e-6), CD4+ T cells (r = 0.216, P = 5.54e-5), macrophages (r = 0.323, P = 1.0e-9), neutrophils (r = 0.233, P = 1.27e-5), and dendritic cells (r = 0.245, P = 5.0e-6)." (PMID 34513707, 2021). "Our study demonstrates for the first time that GGT7 is a novel player in GBM growth and that GGT7 plays a critical role in tumorigenesis by regulating the anti-oxidative damage occurring within the tumor cells." (PMID 25884624, 2015). "To determine if GGT7 plays a functional role in GBM tumorigenesis, we conducted in vivo tumor growth assays in NOD SCIDγ (NSG) mice." (PMID 25884624, 2015).
cancer (3 papers, 2015 to 2025). A tumor composed of atypical neoplastic, often pleomorphic cells that invade other tissues. "This discrepancy was evident when only GGT7 was found to interact with proteins associated with lung cancer, indicating it could play a role in cancer progression." (PMID 25884624, 2015). "Our results showed that prostate tissues expressed four major isoforms of GGT family genes (GGT1/5/6/7), of which GGT1 expression was upregulated but GGT6/GGT7 expression was downregulated in cancer tissues compared to benign tissues." (PMID 40094020, 2025). "Since other members of the GGT family were found to be altered in a variety of cancers, we hypothesized that GGT7 could regulate GBM growth and formation." (PMID 25884624, 2015). "Compared to case-matched benign tissues, most cases of cancer tissues expressed higher GGT1/GGT5 genes but lower GGT6/GGT7 genes, of which GGT6 expression showed a dramatic reduction in cancer tissues." (PMID 40094020, 2025).
GGT7 also shares sentences with these, for which no sentence is quoted: endometrial cancer (2 papers); bipolar disorder (1); breast carcinoma (1); chronical atrial fibrillation (1); hepatocellular carcinoma (1); Hernia (1); liver cancer (1); lung carcinoma (1); major depression (1); melanoma (1); ovarian carcinoma (1); pancreatic ductal adenocarcinoma (1); renal carcinoma (1).